AKT1 (AKT serine/threonine kinase 1)
Diseases named in the same sentence as AKT1 in open-access papers (continued):
Sharing a sentence is not in itself a finding about the gene and the disease.
colon carcinoma (continued). "The 24 h migration distance of oe-AKT1-control cells was significantly longer than that of NC-control cells (both, P < 0.001), indicating that overexpression of AKT1 could enhance the healing ability of colon cancer cells." (PMID 31772677, 2019). "However, a decreased p-Akt1 expression was observed in Hes1-inhibited colon cancer cells in comparison with that in the control cells." (PMID 26452029, 2015). "We have also analyzed the radiation sensitivity of the colon cancer cells sorted for CD133high/CD44high and CD133low/CD44low expression, and further investigated the influence of two AKT isoforms (AKT1, AKT2) on CD133 and CD44 expression, including CD44 splice variant isoforms." (PMID 24760019, 2014). "Glu17 on protein AKT1 plays an important role during ligand-binding (PDB ID: 1H10), which is a highly frequent, mutated residue in multiple cancer types, including breast, skin melanoma, lung, and colon cancers." (PMID 25360158, 2014). "However, the difference between the migration distances of the two si-AKT1 groups was smaller than that between the NC-control and NC-JSD groups (both, P < 0.001), suggesting that the ability of JSD to inhibit the healing ability of colon cancer cells was weakened after AKT1 knockdown." (PMID 31772677, 2019). "In this regard, the authors assessed the in vitro and in vivo effects of resveratrol using AKT1 knockdown SW480 and SW620 colon cancer cells and a lung metastasis model of colon cancer (nude mice inoculated with SW480 cells)." (PMID 36829966, 2023). "For example, it has been reported that knockout of ISOC1 activates the AKT1/GSK-3β pathway and induces the apoptosis of colon cancer cells." (PMID 36144632, 2022). "Beside small molecules, the combination of plant extracts including resveratrol targeted AKT1 and quercetin targeted PIK3CG were proved to be useful for colon cancer." (PMID 32523951, 2020). "The m6A methyltransferase inhibitor SAH 75 elevated the expression of AKT1, PTEN, mTOR, and PIK3CA in stomach and colon cancer cell lines." (PMID 32863943, 2020). "HCT116 colon cancer cells with stable AKT-knock-out and siRNA-mediated AKT-knockdown phenotypes were used to investigate the role of Akt1 and Akt2 isoforms in HR." (PMID 31847370, 2019). "Conversely, overexpression of AKT1 and activation of the AKT/GSK-3β signaling pathway enhanced JSD's ability to inhibit EMT and colon cancer metastasis." (PMID 31772677, 2019). "For EMT reversion and metastasis inhibition in colon cancer cells, JSD has weaker effects in AKT1-silenced cells and more powerful effects in AKT1-overexpressed cells, which can also be observed in corresponding in vivo studies." (PMID 31772677, 2019). "Our study found that the inhibition effects of JSD on colon cancer EMT and metastasis were weakened with knockdown of AKT1 and inactivation of AKT/GSK-3β signaling." (PMID 31772677, 2019). "To analyze AKT isoform-specific expression and activation, we first characterized AKT specific antibodies using a set of parental and AKT knockout HCT116 colon cancer cells (AKT1−/−, AKT2−/−, and AKT1/AKT2 DKO)." (PMID 30012111, 2018). "Taken together, our results present strong support for the role of both AKT1 and AKT2 isoforms in the response to ionizing radiation and their interaction with DNA-PKcs and MRE11 in colon cancer cells." (PMID 24338765, 2014).
colon carcinoma (continued). "A somatic mutation in the coding sequence of the AKT1 gene previously identified in breast, ovarian and colon cancers could not be identified in a panel of 109 GBM samples and 9 high-grade astrocytoma cell lines, indicating that AKT activation in GBMs was not mediated by this activating mutation." (PMID 20515495, 2010). "Similarly to resveratrol treatment, the deletion of AKT1 and AKT2 in colon cancer cells inhibits cell proliferation and colony growth by delaying cell cycle progression and increasing apoptosis in the cells." (PMID 36080453, 2022). "Indeed, we recently found that in addition to blocking cullin neddylation as a potent NAE inhibitor, MLN4924 also activates EGFR and downstream AKT1 and ERK1/2 signals by triggering EGFR dimerization in lung, breast and colon cancer cells." (PMID 33263949, 2021). "Our results indicated that EcN could elicit apoptotic impacts on the colon cancer HT-29 cells by up-regulating PTEN and Bax and down-regulating AKT1 and Bcl-xL genes." (PMID 32774810, 2020). "Resveratrol is considered to be a promising anticancer drug for chemoprevention or therapy for colon cancer, targeting numerous cellular molecules, such as AKT serine/threonine kinase 1 (AKT1), AKT2, and AKT/GSK-3β/Snail signaling pathway, and increasing ROS production." (PMID 32244860, 2020). "In addition, the number of migrated and invaded cells in the oe-AKT1-control group was significantly higher than that in the NC-control group (all, P < 0.001), indicating that AKT1 overexpression could enhance the migration and invasion potential of colon cancer cells." (PMID 31772677, 2019). "Oncogenes including AKT1, JUN, SRC are a gene set that are also prominent in colon cancer." (PMID 30774816, 2018). "In the present study, we demonstrated the suppressive effect of InsP6, a natural occurring phytochemical, on the expression and activity of key components of the AKT/mTOR signaling axis including AKT1 and p70S6K1 in colon cancer cells as significant regulators of proliferation and apoptosis." (PMID 28972559, 2017). "The CSCs with CD44+High and CD133+High expression are highly radio-resistant in colon cancer, and they also have higher expression of AKT (AKT1/2) compared to CD44Low and CD133Low cells, indicating their capacity for higher DNA repair and the ability to escape cell death/apoptosis post radiotherapy." (PMID 27825361, 2016). "Further immunoblotting analysis revealed that in contrast to other cancer types, PME‐1 silencing did not inhibit expression of active phosphorylated forms of serine–threonine‐specific protein kinases AKT‐1/2/3 (p‐AKT) and ERK‐1/2 (p‐ERK) in either of the colon cancer cell lines." (PMID 26377365, 2015). "The CD133 expression was reduced in the AKT1 KO but not AKT2 KO colon cancer cell line, whereas the expression of CD44 was increased by both AKT1 KO and AKT2 KO." (PMID 24760019, 2014). "Furthermore, the targeted inhibition of AKT1 and AKT3 prevented glycolysis-related enzyme activation, significantly blocked the production of lactate and diminished the migration and invasion of chemoresistant colon cancer cells." (PMID 38396845, 2024). "Additionally, JSD could lead to an increase in expression of E-cadherin, and a decrease in expression of N-cadherin, Vimentin, p-AKT1, AKT1, p- GSK-3β, Snail, Slug, and Twist in colon cancer cells." (PMID 31772677, 2019). "However, the difference between the si-AKT1-control and si-AKT1-JSD groups was less than that between the NC-control and NC-JSD groups (all, P < 0.05), suggesting that the ability of JSD to reverse EMT in colon cancer cells was mitigated by AKT1 knockdown." (PMID 31772677, 2019).
colon carcinoma (continued). "Moreover, the difference between in the oe-AKT1-control and oe-AKT1-JSD groups was significantly larger than that between the NC-control and NC-JSD groups (both, P < 0.05), suggesting that the ability of JSD to reverse EMT status in colon cancer cells was enhanced by AKT1 overexpression." (PMID 31772677, 2019). "Moreover, the difference between in the oe-AKT1-control and oe-AKT1-JSD groups was more than that between the NC-control and NC-JSD groups (both, P < 0.001), suggesting that the ability of JSD to inhibit the migration and invasion of colon cancer cells was enhanced after AKT1 overexpression." (PMID 31772677, 2019). "However, the difference between the si-AKT1-control and si-AKT1-JSD groups was smaller than that seen in the NC-control and NC-JSD groups (all, P < 0.001), suggesting that the ability of JSD to inhibit migration and invasion of colon cancer cells was mitigated by AKT1 knockdown." (PMID 31772677, 2019). "Potentially, if AKT1 is inhibited in native (i.e. - no heterologous Par-4 expression) HT29 and SW480 colon cancer cells, then endogenous Par-4 will be activated, sensitizing cells to chemotherapy-induced apoptosis." (PMID 20433755, 2010). "C26 CM upregulated Ddit4, Akt1, and mTOR expression and downregulated phospho-4E-BP1, and phospho-p70S6K in C2C12 compared with CM of CT26, another colon cancer cell line that could not lead to cancer cachexia." (PMID 34175899, 2021).
pancreatic cancer (271 papers, 2003 to 2026). "The vast majority of AKT1 gene missense mutations encompass the PH domain, the most common one being E17K, which has been reported in bladder, breast, ovarian, endometrial, urothelial, colorectal, lung and pancreatic cancers." (PMID 39614261, 2024). "Compound 17 (quercetin-3-methyl ether) interacted with multiple key targets related to pancreatic cancer, including AKT1, EGFR, TNF, CASP3, and SRC, and occupies a central position within the PPI network, indicating the potential regulatory interaction." (PMID 41006588, 2025). "Consistent with in vitro growth results, the Akt1/2/3KO pancreatic tumors progressed the slowest compared to all the other cell lines, and the host mice implanted with Akt1/2/3KO cells had the longest median survival of 86 days." (PMID 38920688, 2024). "AKT1 appears to contribute more to pancreatic cancer growth whereas AKT2 and AKT3 contribute more to phosphorylating downstream targets." (PMID 38920688, 2024). "The difference in the penetrance of the phenotype suggests that other PI3KCA targets in addition to AKT1/2/3 play a mediating role in PI3K’s regulation of pancreatic cancer immunity." (PMID 38920688, 2024). "Pancreas-specific KrasG12D mice sufficiently developed pancreatic intraepithelial neoplasia using a Pdx1 promoter, and active Akt1 cooperated with KrasG12D to accelerate pancreatic carcinoma onset and progression." (PMID 37247123, 2023). "On the other hand, an amplified Akt1 is less frequent since it has been found only in 20% of neuroendocrine prostate cancers, 10% of pancreatic cancers, and 3–5% of breast and serous ovarian cancers." (PMID 33916378, 2021). "In particular, both Akt1 and Akt2 are markedly activated in primary pancreatic tumors and tumor metastases, and Akt2 was positively correlated with resistance of PDAC to chemotherapy." (PMID 32993067, 2020). "Pancreatic cancer cells with silenced AKT1 strongly increased the co-expression of these two CSC markers." (PMID 32764385, 2020). "Similar results were observed for STAT3 phosphorylation on serine-727 and CCR1 mRNA expression in T24 bladder and Capan-1 pancreatic cancer cells expressing AKT1 shRNA." (PMID 29212252, 2017). "The next protein in our list is AKT1, which is serine/threonine kinase AKT (also known as Protein Kinase B) for which we found reports of over-expression in pancreatic tumour formation." (PMID 28871116, 2017). "In addition, by inactivating the Akt1 signaling pathway, miR-149-3p contributed to dioscin’s anti-pancreatic cancer activity." (PMID 41170181, 2025). "Interestingly, Akt1/2KO pancreatic tumors also progressed relatively slowly leading to prolonged host animal survival with a median of 47 days; however, there were no long-term tumor-free survivors." (PMID 38920688, 2024). "For example, ABHD11-AS1 was found to increase levels of p-PI3K and p-Akt1 proteins in pancreatic cancer cells, although the detailed upstream mechanisms remain unknown." (PMID 34375304, 2021). "On the other hand, AKT1 inhibition through arsenic trioxide (which targets a large set of genes) following gemcitabine treatment did not increase chemosensitivity in a Phase II clinical trial for pancreatic cancer." (PMID 29023490, 2017). "In summary, this study identified candidate compounds with inhibitory effects on AKT1 through a series of screening procedures, paving the way for clinical pharmacotherapy studies of AKT1 inhibitory drugs (such as the treatment of ovarian, lung, osteosarcoma, and pancreatic cancers)." (PMID 35603567, 2022). "Therefore, phosphorylation of AKT-1 at Ser473 alone may alter homeostasis and function of immune cells in this murine pancreatic tumor model." (PMID 22132131, 2011). "The study demonstrated that epimedium extract inhibits the expression and phosphorylation of AKT1 and EGFR in the pancreatic cancer cell line PANC-1." (PMID 39011503, 2024).
pancreatic cancer (continued). "AKT1 with TMPRSS2 and FURIN were positively correlated in all contexts except for pancreatic cancer and healthy pancreas, respectively." (PMID 33796097, 2021). "The current results indicate that AKT1, CDKN2A, ERBB2, and IL6 are the common protein core of liver and pancreatic cancers, and STAT3, CASP3, NOTCH1, and CTNNB1 are possible differential proteins that discriminate these cancers." (PMID 35154607, 2021). "The current findings indicate that AKT1, CDKN2A, ERBB2, and IL6 are the critical common hubs related to promoting both liver and pancreatic cancers." (PMID 35154607, 2021). "AKT1, CDKN2A, ERBB2, and IL6 are common protein core of liver and pancreatic cancers, while STAT3, CASP3, NOTCH1, and CTNNB1 are possible differential proteins to discriminate these cancers." (PMID 35154607, 2021). "This pathway inhibition leads to the dephosphorylation and reduced activity of components like 3-phosphoinositide-dependent kinase 1, Akt1, and the mTOR receptor, as well as the BRAF/MKK/ERK1/2 signaling pathway, resulting in cell cycle arrest and apoptosis in pancreatic cancer cells." (PMID 40868211, 2025). "In addition, evodiamine, which targets AKT1 and PI3K, PKA, mTOR and PTEN sensitizes pancreatic cancer cells to gemcitabine." (PMID 29023490, 2017). "Although ΔNp63α contributed to chemoresistance through regulation of Akt1 expression in ovarian and head and neck cancer, we did not observe such effect in pancreatic cancer cells." (PMID 22053213, 2011). "Although no mutations in PI3K or Akt1 have been reported so far, evidence suggests that the PI3K/Akt pathway is active in pancreatic cancers, which indicates that the pathway is a putative therapeutic target in such cancers." (PMID 20423485, 2010).
diabetes (270 papers, 2009 to 2026). "A significant association between SNP on AKT1 gene and severity of COVID-19 by logistic regression adjusted for age, sex, hypertension, diabetes, and cardiopathy." (PMID 39439795, 2024). "Overexpression of AKT1 in RPECs counteracts the retinal abnormalities induced by diabetes, whereas the functional loss of AKT1 in RPECs accelerates retinal vascular damage in diabetic mice." (PMID 37978169, 2023). "Further, overexpressing Akt1 in RPE inhibits diabetes-induced retinal abnormalities and loss of Akt1 function in retina/RPE accelerates retinal vascular damage in diabetic mice." (PMID 36229454, 2022). "Akt2 deficiency in mice was documented to induce hyperinsulinemia, which precludes inhibition of tumorigenesis, and if partial deficiency of Akt1 also occurred, the mice developed hyperglycemia and diabetes." (PMID 35578699, 2021). "As for Akt1, the Akt2 isoform regulates beta-cell growth and survival; however, Akt2 distinctively controls glucose metabolism as Akt2-deficient mice develop diabetes." (PMID 22563476, 2012). "The favourable binding energy of −9.813 kcal/mol for Gymnemic Acid I indicates robust affinity for AKT1, suggesting it may play a role in modulating glycolytic pathways linked to diabetes." (PMID 39810481, 2025). "Researchers consider the role of AKT1 polymorphism as being associated with major metabolic syndrome components, which could be candidates for the incidence of diabetes and NFLD." (PMID 35154608, 2021). "Therefore, diabetes-associated targets (AKT1 and PPARγ) and two targets involved in regulating glucolipid metabolism (GSK3β and ADORA1), which have the lowest free energy binding with their compounds, were selected for molecular docking and refined by exploring the specific binding sites." (PMID 36278175, 2022). "It was found that nine active ingredients in sweet potato leaves act on 90 targets related to diabetes, with the main targets for their blood glucose-lowering effects being AKT1, GAPDH, STAT3, TNF, and EGFR." (PMID 41515064, 2026). "These compounds exhibited strong binding affinities to AKT1 and other diabetes-related targets like IL6 and EGFR." (PMID 40969600, 2025). "In diabetes mellitus, these signals can be dysregulated via one or several of the proteins driving insulin signaling (AKT1, PIK3R1, INSR, PPARG, and PIK3CG)." (PMID 41011980, 2025). "AKT1 plays a pivotal role in the pathogenesis of diabetes, influencing not only glucose metabolism but also fatty acid homeostasis." (PMID 39707185, 2024). "A significant association between SNP in the AKT1 gene and patients admitted to the ICU with severe COVID-19 by logistic regression adjusted for age, sex, diabetes, and cardiopathy." (PMID 39439795, 2024). "In diabetes, impaired AKT1 signaling reduces cellular responses necessary for effective wound healing, such as keratinocyte migration and angiogenesis." (PMID 39512686, 2024). "It is noteworthy that AKT1 exhibited a particularly significant role in diabetes treatment, as it exhibited a strong binding affinity to HYD, with a binding energy below − 5.0 kcal/mol." (PMID 38031191, 2023). "AKT1, VEGFA and IL-6, as enriched targets or downstream key factors of the PI3K-AKT pathway, are relevant factors in the pathogenesis of diabetes." (PMID 36559019, 2022). "To test this, we overexpressed Akt1 in RPE by subretinal injection (SRi) of AAV2-hRPE-GFP-P2A-mAkt1 (once per month) in WT diabetic mice when diabetes induction was confirmed in these mice 7 days post STZ injection." (PMID 36229454, 2022). "The diabetes models with downregulated S6K, Akt1, and chico were complementary to the HSD model in pharmacological research and indicated the effect position of a certainly tested compound on the whole insulin-related pathway." (PMID 36035393, 2022).